CD4 (CD4 molecule)
Diseases named in the same sentence as CD4 in open-access papers (continued):
Sharing a sentence is not in itself a finding about the gene and the disease.
infection (continued). "However, HIV-1 establishes new infections at mucosal surfaces and then in neighboring draining lymph nodes that are both heavily populated with CD4+ T cells and myeloid cells including MΦ." (PMID 35622876, 2022). "To assess the extent to which this high level of infection was due to preferential infection of the AOLHigh and WGAHigh CD4+ Tm cells, we next compared, among the uninfected CD4+ Tm cells and PRE cells, the percentages of cells that were AOLHigh, WGAHigh, or AOLHigh WGAHigh." (PMID 35787792, 2022). "Studies assessing the fate and function of CD4+ T cells during antiviral therapy might contribute to clarifying the impact of CD4+ T cells on infection outcome." (PMID 35215790, 2022). "Even though polyfunctional T cells are associated with better disease control in various infection settings, we did not identify a lack of polyfunctionality in the CD4+ T cells of vaccine breakthrough cases." (PMID 34994081, 2022). "Therefore, it remains a question if the pluripotent memory CD4+ T-cell subset is necessarily contained within the Tfh CXCR5+CCR7+ population in all infection and inflammation contexts." (PMID 35858332, 2022). "If CD4 cells are depleted, the body is vulnerable to infection." (PMID 35205215, 2022). "Restricted expression of CCR5 coreceptor may thus protect essential cells from infection (in particular memory CD4+ T-cells) and preserve immune homeostasis." (PMID 35154162, 2022). "However, we have recently shown that IL-18R/MyD88 signaling intrinsic to CD4+ T cells is critical for Th1 cell proliferation and resistance to apoptosis in response to infection with T. cruzi." (PMID 35670567, 2022). "Here, we hypothesized that if cell-to-cell virus transfer to MDMs proceeds with increased efficiency of CD4 use, compared to infection by cell-free viruses, this might translate into lower sensitivity to Q4120." (PMID 35622876, 2022). "Popliteal lymph nodes of PD-1-/- mice at four and eight weeks post-infection contained significantly more CD4+ and at week eight contained significantly more CD8+ T cells than WT mice, suggesting that expression of PD-1 during B. burgdorferi infection prevents T cell accumulation in the lymph node." (PMID 36265003, 2022). "CD4+ cells facilitate the formation of pathogen-specific memory CD8+ cells during re-infection." (PMID 35930526, 2022). "Moreover, LY6E is up-regulated in the CD4+ T cells of HIV-1-infected individuals during the chronic phase of infection." (PMID 35468127, 2022). "The CD4 T-cell response in infection-naïve adolescents was, however, significantly enhanced by a second dose of vaccine, again indicating the requirement for two vaccine doses in infection-naïve adolescents." (PMID 35720281, 2022). "Overexpression of TIGIT by lentivector infection could hinder the function of CD4+ T cells, such as diminished IFN-γ and IL-17 production, and increased IL-10 expression." (PMID 35720417, 2022). "Thus, influenza virus infection results in the development of antigen-specific, lung-resident CD4+CD69+CD11a+ T cells that persist at least seven months after infection." (PMID 36275685, 2022). "Given the dual roles of LANCL2 and the increasing importance of metabolism on regulating immune signaling, modeling LANCL2 effect on CD4+ T cell differentiation during infection such as CDI may prove to be valuable in defining new therapeutic opportunities." (PMID 36418318, 2022). "We detected a similar breadth of the CD4+ T‐cell response in terms of the number of peptides recognised in unvaccinated COVID‐19 patients, vaccinated individuals (‘V2/V3’) and patients with a combination of vaccination and infection (‘IV/VI’)." (PMID 35957961, 2022). "We therefore next questioned whether reduction of productive infection following SPHK inhibition would be observed equally among CD4 T cells expanded from biologically male and female blood donors." (PMID 35412343, 2022). "HIV-1 Env spike supports both cell-free and cell-to-cell infection of CD4+ T cells." (PMID 35215997, 2022).
infection (continued). "CD4+ T cells are considered to be closely related to the infection with Eg." (PMID 35211114, 2022). "Therefore, oxidative stress during infection contributes to the inflammatory response, with an increase in CD4+ T cells and DC." (PMID 35682626, 2022). "To address if the worm-induced accumulation of CD4+ T cells in the skin persisted over time and following deworming treatment, we assessed skin CD4+ T cells for up to 10 weeks after infection, when most of our animals have naturally cleared the infection." (PMID 34931000, 2022). "The consistency between the alleviated disease and increased CD4+ T cells of the Fcgr1−/− mice in the late infection hinted that CD4+ T cells might act as a main regulatory target of FcγRI." (PMID 36677333, 2022). "Infection of the murine intestine by T1L results in priming and activation of Th1 CD4+ T cell responses, but mediators of these T cell responses are unknown." (PMID 35993365, 2022). "Furthermore, CD4 T cells differentiation into various subsets, e.g. Th1 and Th2, has been shown to have an important role in influencing the clinical outcome of infections such as HIV." (PMID 35757770, 2022). "Strong CD4 T cell responses were present against wt and mutant SARS-CoV2 variants, including the delta (B.1.617.2) strain, in fully vaccinated individuals, whereas they were partly weaker 1 year after natural infection." (PMID 35468147, 2022). "Following stimulation, splenocytes were discovered to overexpress IL-17A, which has been hypothesized to produce CD4+ cells that occupy the lung post-infection and produce chemokines that recruit IFN-γ secreting CD4+ T cells to help control the infection." (PMID 35482149, 2022). "EMRA CD4+ T-cells are important memory immune cells in inflammation and infection." (PMID 36552753, 2022). "Furthermore, using IL-10 reporter (Vert-X) mice, it has been found that NK cells, CD8+ and CD4+ T cells, B cells and plasma B cells represent potential cellular sources of IL-10 during the acute phase (first 10 days post-infection) of T. b." (PMID 35464430, 2022). "Our data shows that heterotypic polyfunctional CD4+ T-cell responses to BA.1 do occur following ancestral SARS-Co2/Alpha/Delta infection (Cohort 1) but are lower than those observed following natural BA.1 infection (Cohort 2), and the latter group mounted robust BA.1 specific T-cell responses." (PMID 35927279, 2022). "The relative expression level of T-bet by CD4 T cells responding to infection may play a particularly important role in establishing tissue-resident memory (TRM) populations, at least in the lung." (PMID 36358898, 2022). "However, the levels of CD4+ T cells induced by M. bovis isolate infection were lower than the ones obtained by Mtb infection (p = 0.04), while the CD4+ T cell levels induced by Mbt infection were higher than Mbb infection (p = 0.02)." (PMID 35456728, 2022). "HIV infection could be successfully inhibited with MVC, indicating that infection is mediated through the CD4 and CCR5 co-receptors." (PMID 35458559, 2022). "Regulatory CD4+ T-cells have been associated with weaker HIV-specific cellular immune responses and been shown to suppress HIV-induced immune hyperactivation and thus, limit infection of conventional CD4+ T-cells." (PMID 35784304, 2022). "Together, the findings from our studies implicate the likely importance of direct infection of sub-optimally activated T cells in establishment of latently infected reservoirs in vivo, especially in CD4 lymphocytes that surround productive viral foci within immune tissue microenvironments." (PMID 35895672, 2022). "The response of intracellular IFN-γ, IL-17A, and IL-21 expressing CD4+ or CD8+ effector T cells in HBV resolved infection was significantly higher than observed in OBI or CHB (P < 0.05), while the concentration of circulating IL-17A was higher in OBI and CHB (P < 0.01)." (PMID 35464946, 2022).
infection (continued). "It is very important to assess the levels of virus-specific CD4+ T cells responses because different Th subsets play a main part in the synergy between innate and adaptive immunity, leading to more effective and successful infection control." (PMID 36146622, 2022). "Likewise, they also induce a largely Th1 cellular immune response, increasing the levels of CD8+ and CD4+ T-cells to fight off current infection and confer immune memory for future infection." (PMID 36012562, 2022). "While CD8+ T cells are important in attacking infected or malignant cells, CD4+ T cells are responsible for the recruitment of cytotoxic T cells to sites of infection, mediating the humoral antibody response, and regulating innate and acquired immune cell activation and proliferation." (PMID 35634279, 2022). "The data presented thus far suggest that although there are differences between blood vs. the tissue sites examined, fucose and sialic acid are upregulated on HIV productively infected cells, and CD4+ T cells expressing high levels of fucose or sialic are preferentially targeted for infection." (PMID 35787792, 2022). "This process might be mediated by the induction of splenic Tregs in vivo, since the depletion of MGL2+ cells conferred mice with partial resistance to the infection and abrogated the increase of CD4+/CD25+ FoxP3+ Tregs induced by the parasite." (PMID 36271272, 2022). "At day 18 after infection, we observed proliferative responses of CD4+ spleen T-cells." (PMID 36510306, 2022). "Here, we studied the preexisting T cells elicited by either vaccination with the mRNA-based BNT162b2 vaccine or by natural infection with ancestral SARS-CoV-2 for their cross-reactive potential to 20 selected CD4+ T-cell epitopes of spike-protein-harboring Omicron BA.1 mutations." (PMID 35891550, 2022). "Studies have shown that immunity generated by flaviviruses sharing the CD4+ T cell epitope promotes protection during subsequent heterologous infection, which is speculated to be mediated by the NS3 protein." (PMID 36444358, 2022). "We therefore addressed the question whether improved efficiency of MDM infection through virus cell-to-cell transfer was due to an increased efficiency of CD4 and/or coreceptor usage." (PMID 35622876, 2022). "This might reinforce the concept that patients experiencing a more severe infection present impaired CD4+ and CD8+ T cell functionality due to an exhausted phenotype." (PMID 35887351, 2022). "Our results revealed that the percentage of the IAV-specific IFN-γ positive CD4+ T cells was higher in the IAV single infection group (0.95 ± 0.1%) compared to that of IAV + SARS-CoV-2 (0.71 ± 0.01%, P = 0.018) and SARS-CoV-2 + IAV (0.35 ± 0.06, P < 0.0001) coinfection groups." (PMID 35107382, 2022). "After infection, the percentage of CD4+T cells and the ratio of CD4+/CD8+T cells in group DIO-E." (PMID 35720836, 2022). "Recently, populations of CD4+, CD8α+, and non-CD4+CD8α+ T cells in the liver and spleen of turkeys were induced following administration of attenuated H. meleagridis as a putative vaccine and subsequent virulent infection." (PMID 35601402, 2022). "At day 9 post infection, flow cytometry showed that ERαKO mice had more T cells present and targeted RNA sequencing revealed increased expression of CD4 and FOXP3, suggesting that ERαKO mice had increased numbers of regulatory T cells compared to ERβKO and WT mice." (PMID 36636722, 2022). "This refinement is also key for detailed incident follow‐up of individual cases and may contribute to the development of statistical models that use CD4 count information to estimate time since infection." (PMID 36069144, 2022). "The tracking of virus-specific CD4 T cells into the lung post-infection, using both MHC class II: peptide tetramers and flow cytometry to identify the cells elicited by infection with IBV, indicate that these IBV-elicited cells in the lung express prototypic cell surface markers of tissue residency." (PMID 35215193, 2022).
infection (continued). "Vaccine-induced, relatively more abundant, SARS-CoV-2–specific CD4+ T cells can eliminate infected monocytes, immune cells implicated in CRS and systemic inflammatory syndrome, and halt disease progression and prevent severe infection." (PMID 35230977, 2022). "Despite the importance of CD4+ T cells in controlling spirochete levels in mouse skin, joint, bladder and heart, Borrelia is maintained in mice for at least one year following initial infection." (PMID 36265003, 2022). "After having established that CD4 T cells of diverse antigen specificity are elicited by IBV and that many of the elicited CD4 T cells are recruited back into the lung post-infection, we sought to examine the localization of the elicited CD4 T cells within the lung compartments." (PMID 35215193, 2022). "It is likely that an older age and lower amount of KRG in non-B may have played a role in the observed faster annual decrease in CD4+ T cells (AD) compared to that found with subtype B infection." (PMID 36312730, 2022). "Our key findings in this study were that natural infection elicits a considerably broader CD4+ epitope response than AVP vaccination and, at least in the setting of natural infection, PA is a very epitope-rich sequence, with epitopes spanning the entire length of the protein." (PMID 36298436, 2022). "There was a skewing of the CD4/CD8 T cell response between the different infection routes." (PMID 35898505, 2022). "The results from our current studies implicate the likely importance of direct infection of sub-optimally activated T cells in establishment of latently infected reservoirs in vivo, especially in CD4 T lymphocytes that surround productive viral foci within immune tissue microenvironments." (PMID 35895672, 2022). "Since a loss of CD4+ T cells, mainly TH17 cells, is seen during infection, especially in the GI tract, it may be possible that the appearance of NKB cells could lead to a loss of CD4+ T cells." (PMID 35311549, 2022). "On day 14 post-infection, mouse lungs infected with the csn1201Δ strain showed substantially fewer total leukocytes, monocytes, T cells (including both CD4 + T cells and CD8 + T cells), B cells, and eosinophils, but significantly more dendritic cells than in the WT-infected mouse lungs." (PMID 35720283, 2022). "Ribose 5-P and S7P levels increase in HIV-1 infected CD4+ T cells 24 hours post-infection." (PMID 36467738, 2022). "We developed a co-culture model using CD4 T cells isolated from the lungs of infected mice and M. tuberculosis-infected murine bone marrow-derived macrophages (BMDMs) to investigate mechanisms of CD4 dependent control of infection." (PMID 35877763, 2022). "Higher CD4 counts may be due to new infection and taking ART for a long period of time also dramatically improves the number of CD4 counts." (PMID 35991634, 2022). "Most of the mutations did not impact the ability of MX2 to inhibit infection as measured by challenging U87-MG CD4/CXCR4 cells with a GFP-encoding HIV-1-based vector (HIV-1/GFP) and enumerating the number of GFP-positive cells at 48 h." (PMID 35880880, 2022). "Thus, the actions of memory T cells against secondary infection and the cross reaction of CD4+T cell requires further explanation and studies to be understood fully." (PMID 36159640, 2022). "Early CD4 counts are a measure of the severity of the infection due to T/F strains." (PMID 35271687, 2022). "Indeed, in the absence of residual parasites, long-lived pathogen-independent CD4+ central memory T cells become tissue-homing effector cells upon a secondary infection and mediate protection through effector memory T cells." (PMID 35967864, 2022). "CD4+ T lymphocytes play an important role in the infection of M. tuberculosis." (PMID 35899049, 2022). "In addition, this study detected IFN-γ-producing memory CD4+ T cells in the rGP19-immunized mice and later infected with E. canis on day 14 post-infection period using flow cytometry." (PMID 36006302, 2022).
infection (continued). "Therefore, the decline rate of the CD4+ T-cell count was calculated more from diagnosed time than from the time of infection." (PMID 35910646, 2022). "There may be additional integrin-dependent or -independent mechanisms contributing to the productive infection of resting CD4+ T cells in the presence of ECs." (PMID 34465136, 2022). "(C) Quantified distribution of IL-4eGFP+CD4+ cells in UMAP gates over the course of Nb infection." (PMID 35950748, 2022). "Earlier study has revealed that mice could survive IBV challenge infection even upon antibody and B cell depletion, due to the presence of CD4+ and CD8+ T cells." (PMID 35884922, 2022). "Further studies using a combination of CD4+ T cell detection methods in concert may help clarify the relative contributions of high and low affinity cells to infection- and vaccine-induced immunity." (PMID 35857584, 2022). "There was the possibility of rGP19 provoked CD4+ memory T cell responses due to the detection of the antigen-specific IFN-γ-producing memory CD4+ T cells in the rGP19-immunized mice later infected with E. canis on day 14 post-infection period." (PMID 36006302, 2022). "Subsequent studies, mainly focused on the visceral form of the infection pointed to the role of IL-17, produced by Th17 subset of CD4+ T cells that along the neutrophils were shown to have important yet equivocal functions in protection against or exacerbation of the infection." (PMID 35090305, 2022). "Pathogen-specific CD4 Th1 cells develop from naïve precursors that are initially activated in the draining lymph node by dendritic cells bringing foreign antigen from the local site of infection." (PMID 35196366, 2022). "Importantly, SARS-CoV-2 specific CD4+ T cell responses too have been demonstrated to be more robust compared to the CD8+ T cell response in the context of vaccination as well as infection." (PMID 36268023, 2022). "A progressive decline of CD8 T cell responses, up to their attrition, was also reported in LCMV-infected mice that were unable to clear the infection because of CD4 T cell depletion, compared to mice with a finite duration of infection, either acute or protracted." (PMID 35740243, 2022). "However, if the patients have treatment failure, HIV progressively kills the cells like CD4 T cells that help protect the body from infection, leading to complications." (PMID 35031007, 2022). "By comparison, only a small portion (~ 5%) of the CD4 T cells in HLAC are able to support productive infection by HIV, However, these productively infected cells provide the source of virus driving abortive infection of bystander cells, which depends on cell-to-cell viral transmission." (PMID 35784348, 2022). "These concurrent infections are the result of the decreased CD4+/CD8+ ratio." (PMID 36425135, 2022). "infection had the lowest CD4+/CD8+ ratio in our investigation." (PMID 36425135, 2022). "We then determined the relative inhibition of infection in CD4 T cells expanded from both sexes." (PMID 35412343, 2022). "In contrast, infection with viral integration occurs in memory CD4+ and CD8+ T-cells." (PMID 35377924, 2022). "During natural infection, CD8+ T cells play an important complementary role to contain the infection through their ability to eliminate already infected cells, while CD4+ helper T cells, amongst other functions, provide signals that support the development of Ab responses." (PMID 34352148, 2022). "Of note, pre-existing immunity to influenza, either due to prior infection or vaccination, seems indeed to impact SARS-CoV-2-specific T-cell immune responses, since it has been associated with enhanced SARS-CoV-2-specific CD4+ T cell immunity and reduced rate of COVID-19." (PMID 36305904, 2022). "Furthermore, VACV∆C7L infection caused marked increase of CD4+ and CD8+ T cells in the BAL compared with WT VACV or PBS mock infection control." (PMID 35351885, 2022).